FGF11 (fibroblast growth factor 11)
Description:
Probably involved in nervous system development and function.
Synonyms: FGF-11; FHF-3; FHF3; FLJ16061; MGC45269; MGC102953
Tractability: No criterion of Open Targets' tractability assessment is met for any kind of drug.
Gene: Protein-coding gene on chromosome 17 (7,438,265 to 7,444,937, forward strand). Ensembl gene ENSG00000161958.
Subcellular location (Human Protein Atlas): Centrosome
Pathways (Reactome):
Muscle contraction: Phase 0 - rapid depolarisation
Gene Ontology:
Molecular function: protein binding; growth factor activity; sodium channel regulator activity
Biological process: cell-cell signaling; nervous system development; neurogenesis; signal transduction
Cellular component: cytoplasm; nucleus
Genetic constraint (gnomAD): Loss-of-function variants: 21 observed, 21.04 expected, observed/expected ratio (o/e) 1, 90% interval 0.71 to 1.44. The upper end of that interval is the gene's LOEUF score, 1.44, which puts it in group 5 of 6, group 1 being the genes least tolerant of losing a copy. Missense variants: 289 observed, 253.92 expected, observed/expected ratio (o/e) 1.14, 90% interval 1.03 to 1.25. Synonymous variants: 117 observed, 97.83 expected, observed/expected ratio (o/e) 1.2, 90% interval 1.03 to 1.39.
Homologues: Orthologues: dog FGF11 (98% identical), guinea pig FGF11 (98% identical), rabbit FGF11 (97% identical), mouse Fgf11 (97% identical), chimpanzee FGF11 (88% identical), rat Fgf11 (77% identical), macaque FGF11 (76% identical), pig FGF11 (76% identical), tropical clawed frog fgf11 (68% identical), zebrafish fgf11a (68% identical), zebrafish fgf11b (64% identical). Paralogues in human: FGF13 (58% identical), FGF14 (55% identical), FGF12 (46% identical), FGF20 (28% identical), FGF9 (28% identical), FGF3 (27% identical), FGF16 (26% identical), FGF4 (26% identical), FGF5 (26% identical), FGF22 (24% identical), FGF10 (24% identical), FGF6 (23% identical), and 9 more.
Diseases named in the same sentence as FGF11 in open-access papers:
FGF11 is named in the same sentence as 29 diseases in open-access papers, as found by Europe PMC text mining. Sharing a sentence is not in itself a finding about the gene and the disease. The quoted sentences say what the papers report.
nasopharyngeal carcinoma (5 papers, 2020 to 2025). A carcinoma arising from the nasopharyngeal epithelium. "For example, in nasopharyngeal carcinoma, exosomal miR-24-3p suppresses T cell proliferation and differentiation by targeting fibroblast growth factor 11 (FGF11), thereby facilitating tumor immune escape and contributing to tumor pathogenesis." (PMID 41019058, 2025). "In recent research, it was revealed that miR-24-3p hinders T cell activity by targeting FGF11 in nasopharyngeal carcinoma (NPC)." (PMID 34680611, 2021). "Relatedly, nasopharyngeal carcinoma (NPC) exosomal miR-243 targeted FGF11 to inhibit T cell proliferation and induce Tregs to not only differentiate, but also impair T cell function." (PMID 37671150, 2023).
Obesity (4 papers, 2022 to 2025). Accumulation of substantial excess body fat. "Considering the role of hypothalamic FGF11 in the whole-body metabolism, it is likely that the increase in Fgf11 gene expression is associated with the progression of obesity." (PMID 36064426, 2022). "A previous study has shown that inhibition of FGF11 in the hypothalamus prevented diet-induced obesity and enhanced BAT thermogenesis via the sympathetic nervous system." (PMID 37446019, 2023). "Therefore, the expression of Fgf11 can be regulated under physiological conditions such as fully developed obesity although it is not clear whether the increase in Fgf11 gene expression is a cause or result of the development of obesity." (PMID 36064426, 2022). "Altogether, these results suggest that ARC Fgf11 knockdown prevents obesity including overweight, increase in adiposity, and attenuation of glucose metabolism." (PMID 36064426, 2022). "Overall, our study highlights the importance of FGF11 as a potential therapeutic target for the treatment of obesity." (PMID 36064426, 2022). "A recent study by Kim and colleagues further expanded our understanding by showing that silencing FGF11 in the hypothalamus of mice prevents metabolic disorders in diet-induced obesity, highlighting the important role of FGF11 in regulating metabolism at the central level." (PMID 40585885, 2025). "The present study contributes to our understanding of the metabolic role of FGF11 in the ARC, highlighting FGF11 as a potential target for the treatment of obesity." (PMID 36064426, 2022).
bladder cancer (3 papers, 2021 to 2023). "Recently, FGF11, as part of a six-gene signature, has been linked to a worse prognosis in bladder cancer, and macrophage-specific FGF12 accelerates the development of liver fibrosis in mice." (PMID 37108717, 2023). "In the future, liver fibrosis and bladder cancer may be treated with therapeutic methods that block macrophage FGF12 and FGF11 expression." (PMID 37108717, 2023). "Among these five genes (GPC2, SETBP1, FGF11, APOL1, H1–2) related to the prognosis of patients with BC, there are no reports or experiments about these genes related to bladder cancer, except for H1–2." (PMID 34315402, 2021).
prostate carcinoma (3 papers, 2017 to 2023). A carcinoma that arises from epithelial cells of the prostate gland. "FGF11-miR-541 activity in response to T-cell infiltration in prostate cancer contributes to prostate cancer cell invasion, likely through suppression of androgen receptor and matrix metallopeptidase 9 (MMP9) activity." (PMID 34068954, 2021). "Furthermore, immunohistology results of prostate cancer showed lower expression of AR and higher expression of MMP9 and FGF11." (PMID 36836690, 2023). "Regardless of the T cell / prostate cancer mechanism, MMP9 expression by osteoclasts was also not modulated by FGF11." (PMID 28097375, 2017).
thyroid cancer (3 papers, 2023 to 2024). "A recent study on thyroid cancer found that FGF11 knockdown prevents hypoxia-induced tumor cell invasion, migration, and proliferation." (PMID 38542288, 2024). "Hypoxia is a significant cause of metastasis and recurrence in cervical lymph nodes of PTC, and mechanistic studies reveal that in a hypoxic environment, FGF11 forms a positive feedback loop with HIF1α, which in turn promotes thyroid cancer growth and metastasis." (PMID 38902782, 2024). "FGF11 interacted with HIF1A to increase thyroid cancer growth and metastasis." (PMID 36937508, 2023). "Consequently, FGF11 and HIF-1α establish a positive feedback loop that aids in the development and spread of thyroid cancer." (PMID 38542288, 2024).
giant cell tumor of bone (2 papers, 2017 to 2019). "FGF11 expression was evident in large multinucleated cells morphologically resembling osteoclasts in representative cases of rheumatoid arthritis (RA) and giant cell tumour of bone (GCTB)." (PMID 28097375, 2017). "Furthermore, FGF11 protein is strongly expressed in osteoclasts in osteolytic diseases such as rheumatoid synovium and giant cell tumor of bone, suggesting that it plays a role in pathological bone resorption." (PMID 31288483, 2019).
Hepatic fibrosis (2 papers, 2019 to 2023). The presence of excessive fibrous connective tissue in the liver. "We did not identify direct reports of the role of FGF14 in hepatic fibrosis, but the FGF11-14 subfamily members interact with mitogen-activated protein kinase (MAPK)." (PMID 31031647, 2019).
lung adenocarcinoma (2 papers, 2015 to 2023). A carcinoma that arises from the lung and is characterized by the presence of malignant glandular epithelial cells. "After controlling for tumor purity, we discovered that FGF11 expression levels were strongly linked to 12 T cell markers in lung adenocarcinomas using the TIMER database." (PMID 37250453, 2023). "By combining the Cancer Genome Atlas (TCGA) database analysis with immune infiltration-related information, we were able to identify the differentially expressed gene FGF11, which has been linked to lung adenocarcinoma (LUAD) prognosis." (PMID 37250453, 2023). "We used the TIMER database to analyze the association between FGF11 expression, tumor purity, and immune cell infiltration level in lung adenocarcinoma." (PMID 37250453, 2023). "We analyzed the TCGA database and other bioinformatics sources to determine whether FGF11 is associated with lung adenocarcinoma initiation and progression." (PMID 37250453, 2023). "We found the top 50 genes in lung adenocarcinoma that are positively and negatively correlated with FGF11 levels." (PMID 37250453, 2023). "The expression of FGF11 was also upregulated in lung adenocarcinoma tumor tissues according to the TCGA database." (PMID 37250453, 2023). "The area under the curve was 0.912 in the receiver operating characteristic (ROC) curve, indicating that the high expression of FGF11 can further predict the poor prognosis of lung adenocarcinoma patients." (PMID 37250453, 2023). "We discovered that FGF11 expression is higher in lung adenocarcinoma tissues than in normal tissues." (PMID 37250453, 2023). "First, we obtained data from TCGA database and ImmPort database and analyzed by Venn diagram, and we found that FGF11 is one of 170 differentially expressed genes, which is related to the prognosis of lung adenocarcinoma." (PMID 37250453, 2023). "FGF11 expression remained substantially related to the greatest immunological indicators within distinct kinds of immune cells within lung adenocarcinoma after controlling for tumor purity." (PMID 37250453, 2023). "We discovered a link between FGF11 expression and immune cell markers in lung adenocarcinoma." (PMID 37250453, 2023). "This study aimed to examine the link between FGF11 and the prognosis of lung adenocarcinoma." (PMID 37250453, 2023). "This prompted us to investigate whether FGF11 in the immunological milieu of lung adenocarcinoma increases tumor cell immune escape by boosting T cell exhaustion, thereby contributing to the poor prognosis of lung adenocarcinoma." (PMID 37250453, 2023). "We found that FGF11 expression was higher in the lung adenocarcinoma tissue than in the paracancerous tissue, and patients with high FGF11 expression had a lower overall survival, progression-free survival, and disease specific survival rate than those with low FGF11 expression." (PMID 37250453, 2023). "Of particular interest is the fact that FGF11 was present in the two DCGs lists (lung adenocarcinoma Q-value = 0.037, HNCC Q-value = 0.053), which is an important finding when considering that the methylation array platform in these two cases was the same (Illumina 27K)." (PMID 26029238, 2015). "Patients with lung adenocarcinoma with high FGF11 expression correlated with a shorter OS, PFS, and DSS than those with low FGF11 expression." (PMID 37250453, 2023). "Therefore, we hypothesize that FGF11 in the lung adenocarcinoma microenvironment increases tumor immune escape by increasing T cell depletion and exhaustion, contributing to the poor prognosis in patients with lung adenocarcinoma." (PMID 37250453, 2023). "We also found that that patients with lung adenocarcinomas with a high FGF11 expression experienced lower OS, PFS, and DSS compared to those of patients with a low FGF11 expression." (PMID 37250453, 2023).
lung carcinoma (2 papers, 2021 to 2023). "A previous study showed that copy number variations (CNVs) of FGF11 gene was correlated with the risk of lung cancer in heavy smokers, suggesting a potential role of FGF11 in lung cancer initiation." (PMID 34404435, 2021). "The link between FGF11 and lung cancer clinical data was investigated using TCGA and Kaplan–Meier (KM)-plotter databases, and we developed a prediction model." (PMID 37250453, 2023). "Using the lung cancer information within the KM-plotter database, we examined the prognosis of patients with varying FGF11 levels." (PMID 37250453, 2023). "In addition, hypoxia induced factors-1 alpha (HIF-1α) plays a key role in hypoxia signaling pathways which is dysregulated lung cancer, we next explored whether FGF11 level regulates the expression of HIF-1α in A549 and NCI-H460 cells." (PMID 34404435, 2021). "Thus, we conducted a correlation study between FGF11 and EGFR (19DEL, L858R), EGFR (Exon 20ins), KRAS (G12C), ALK, ROS1, BRAF, NTRK1/2/3, MET, and RET, which are all recommended by the NCCN guidelines for the diagnosis of nonsmall cell lung cancer." (PMID 37250453, 2023).
breast carcinoma (1 paper, 2023). "FGF11 and FGF18 were also found to be associated with MBD in our cohort, however limited information exists on their role in MBD or breast cancer." (PMID 37546410, 2023).
giant cell tumour (1 paper, 2017). "FGF11 was also abundantly expressed in osteoclasts within the rheumatoid synovium and in giant cell tumour of bone." (PMID 28097375, 2017).
hepatocellular carcinoma (1 paper, 2023). A malignant tumor that arises from hepatocytes. "The expression and activation of HIF-1α and FGF11 inevitably needs to be considered for evaluating prognosis and therapeutic options for HBV-derived hepatocellular carcinoma." (PMID 37646922, 2023).
meningioma (1 paper, 2012). A generally slow growing tumor attached to the dura mater. "Expression of FGF2, FGF7, FGF9, and FGF11 was significantly increased 3.19-, 48.32-, 27.15-, and 3.34-fold respectively in fibroblastic meningiomas compared with arachnoidal tissue by qRT-PCR." (PMID 23285163, 2012). "We found that several growth factors including EGFL6, IGF1, FGF2, FGF7, FGF9, and FGF11 were overexpressed in fibroblastic meningioma, especially EGFL6 gene with extremely high expression in benign meningioma tissues." (PMID 23285163, 2012).
neuroblastoma (1 paper, 2017). Neuroblastoma (NB) is the most common solid, extracranial childhood tumor. "To determine if FGF11 is induced by hypoxia in nervous tissues, we analysed gene expression profiles in SH-SY5Y human neuroblastoma cells." (PMID 28074842, 2017).
oral squamous cell carcinoma (1 paper, 2015). "Elevated FGF11 expression has been noted in neural precursor cells and cardiomyocytes and increased FGF11 has also been associated with lymphatic spread of an oral squamous cell carcinoma cell line." (PMID 26205789, 2015).
oropharyngeal cancer (1 paper, 2023). Carcinoma, predominantly squamous cell, arising from the epithelial cells of the oropharynx. "Taken together, the data imply that FGF11 may play a major role in the prognosis of patients and that FGF11 could serve as a prognostic marker in HPV-positive oropharyngeal cancer." (PMID 37046615, 2023).
overnutrition (1 paper, 2022). An imbalanced nutritional status resulting from excessive intake of nutrients. "Our study defines the physiological significance of hypothalamic FGF11 in the regulation of metabolism in response to overnutrition such as high-fat diet." (PMID 36064426, 2022).
sarcoma (1 paper, 2024). A usually aggressive malignant neoplasm of the soft tissue or bone. "The rat sarcoma (RAS) pathway was also markedly deregulated and marker genes for cell proliferation were found to be downregulated (e.g., FGF11, PKCA, MAP2K1)." (PMID 38375032, 2024).
tumor (18 papers, 2017 to 2025). "Overexpression of fibroblast growth factor (FGF) family proteins, such as FGF1 and FGF11, is associated with tumor growth, progression, invasion, and metastasis." (PMID 38339062, 2024). "Through the analysis of previously published transcriptomic data, we found that FGF11 was upregulated in NSCLC tumor tissues, which was also associated with poor prognosis of the patients." (PMID 34404435, 2021). "Notably, in general, the protein expression data confirmed the RNA expression data, in which a stronger tumour FGF11 immunoreactivity was associated with a worse survival." (PMID 37046615, 2023). "FGF11 expression, a target of miR-296-3p, was positively regulated by circ-0004851 in rescue experiments, and the suppression of circ-0004851 mitigated the tumor-promoting effects of overexpressed FGF11." (PMID 38902782, 2024). "These outcomes indicate that high iodine promotes tumor growth in the xenograft tumor model and significantly influences the expression of circ_0004851/miR-296-3p/FGF11 in this model." (PMID 38902782, 2024). "In our research, we investigated iodine’s role in PTC progression through the circ_0004851-associated ceRNA network (circ_0004851/miR-296-3p/FGF11 axis) using RNA sequencing, which we subsequently validated in PTC tissues, cells, and xenograft tumor mice." (PMID 38902782, 2024). "In tumor cells, we also found that high baseline expression of specific genes, including PCNA, FGF11, FGF18, CD274 (PD-L1) and HLA-A, was associated with a favorable response." (PMID 38245530, 2024). "In summary, our data confirm that high iodine regulates tumor progression in PTC through the circ_0004851/miR-296-3p/FGF11 pathway." (PMID 38902782, 2024). "We examined the relationship between FGF11 and selected immune cells to determine any effect on the tumor microenvironment (TME)." (PMID 37250453, 2023). "Using the TIMER database, we discovered that higher FGF11 expression was correlated with decreased tumor infiltration of immune cells." (PMID 37250453, 2023). "More specifically, patients with a strong intensity of cytoplasmic FGF11 immunoreactivity in their tumours had a significantly worse OS (44%) as compared to those with a weak tumour reactivity (100%) (log rank, p = 0.006)." (PMID 37046615, 2023). "In this study, we explore the effect of FGF11 expression on tumor cell behavior and the activities in the tumor microenvironment." (PMID 37250453, 2023). "High FGFR1 expression in tumor tissues is associated with less favorable tumor characteristics, and FGF ligand (FGF1, FGF11, FGF18) expression is associated with MBD." (PMID 37546410, 2023). "A recent study evaluated the role of FGF11 in non-small cell lung cancer (NSCLC), and the authors suggested that FGF11 functions as an oncogene in NSCLC tumour progression." (PMID 37046615, 2023). "Intracellular FGFs are suggested to function as intracellular proteins independent of fibroblast growth factor receptors (FGFRs); irrespectively, previous studies have shown the importance of FGF11 for tumour growth, invasion, and metastatic potential." (PMID 37046615, 2023). "Exosomal miR-24-3p mediates T cell suppression by inhibiting FGF11 and participates in tumor pathogenesis." (PMID 35565418, 2022). "CCK-8 proliferation assay demonstrated that FGF11 overexpression promoted the tumor cell proliferation as well as the ability in colony formation, supporting an oncogenic role of FGF11 in NSCLC cells." (PMID 34404435, 2021). "Previously published transcriptomic data (GSE75037 and GSE81089) were used to compare FGF11 expression level between NSCLC tumor tissues and adjacent normal tissues." (PMID 34404435, 2021). "The IHC analysis of Ki67 (cell proliferation marker) in the tumor samples showed that knockdown of FGF11 significantly reduced the percentage of cells expressing Ki-67." (PMID 34404435, 2021). "We found that the expression level of FGF11 was significantly higher in NSCLC tumor tissues than that of normal tissues." (PMID 34404435, 2021).